DHODH (dihydroorotate dehydrogenase (quinone))
Diseases named in the same sentence as DHODH in open-access papers (continued):
Sharing a sentence is not in itself a finding about the gene and the disease.
melanoma (continued). "Additionally, while the MYC family of oncogenes regulates the expression of DHODH, the key enzymes in de novo pyrimidine synthesis, DHODH inhibitors downregulate c-MYC in melanoma, myeloma, and lymphoma cells." (PMID 36814599, 2023). "The importance of DHODH activity for tumor formation was shown by the inability of 4T1 breast carcinoma and B16 melanoma cells lacking the Dhodh gene to form tumors, with restoration of tumor formation after re-expression of the gene." (PMID 33329014, 2020). "Thus, simultaneous pharmacological inhibition of DHODH and BRAF has been reported to decrease the progression of melanoma in cell lines and in mouse xenograft models." (PMID 31108873, 2019). "To determine whether activation of the STING signaling pathway could enhance the antitumor efficacy of DHODH inhibitors, we first evaluated the combinatorial effects of EA6 (0.5 μM) and MSA, a well-characterized STING agonist, in A375 and B16F10 melanoma cells across varying molar ratios." (PMID 41239499, 2025). "Collectively, these findings demonstrate that prodrug H62 overcomes melanoma resistance to DHODH inhibition by simultaneously inducing pyroptosis and recruiting NK cells, thereby amplifying pyroptotic cell death through integrated STING activation and targeted DHODH inhibition." (PMID 41239499, 2025). "However, the exact molecular mechanism of DHODH inhibition-induced cell proliferation suppression in melanoma was not fully elucidated." (PMID 29348830, 2017).
rheumatoid arthritis (24 papers, 2017 to 2026). A chronic, systemic autoimmune disorder characterized by inflammation in the synovial membranes and articular surfaces. "For example, 2 different DHODH inhibitors are approved for the treatment of rheumatoid arthritis (Lef) and multiple sclerosis (MS) (teriflunomide)." (PMID 36453551, 2022). "Later, the DHODH inhibitor leflunomide was approved as an antiinflammatory agent in the treatment of rheumatoid arthritis." (PMID 35943801, 2022). "In fact, DHODH inhibitors are currently in clinical use to treat autoimmune diseases like multiple sclerosis and rheumatoid arthritis, further supporting their usefulness to dampen excessive immune responses." (PMID 35492218, 2022). "Leflunomide is an FDA-approved drug for the treatment of rheumatoid arthritis, and its pharmacological role is to activate Mfn2-mediated mitochondrial fusion by inhibiting dihydroorotate dehydrogenase (DHODH)." (PMID 34868997, 2021). "At standard doses for rheumatoid arthritis, teriflunomide inhibits de novo pyrimidine synthesis via dihydroorotate dehydrogenase (DHODH), and at higher doses suppresses tyrosine and serine kinase activities." (PMID 34276351, 2021). "It is important to note that DHODH-based therapy is most likely a safe approach, since the DHODH inhibitor leflunomide and its active metabolite teriflunomide have been used clinically for chronic diseases, such as rheumatoid arthritis and multiple sclerosis." (PMID 34462431, 2021). "In accordance with previous reports, we have observed cell cycle arrest in the early S phase after inhibition of DHODH activity by leflunomide, a clinically used agent in patients with rheumatoid arthritis and multiple sclerosis." (PMID 32034120, 2020). "Leflunomide is an approved drug for treatment of rheumatoid arthritis and its principle mode of action is inhibition of DHODH and mitochondria-based synthesis of pyrimidines, one of two pathways that typically supply pyrimidines to cells." (PMID 32453724, 2020). "Leflunomide is an approved, well-tolerated, and high-affinity (Kd = 12 nM) small-molecule inhibitor of DHODH used in the treatment of rheumatoid arthritis." (PMID 31841108, 2019). "So far, teriflunomide and its prodrug leflunomide, which are used as immunosuppressors in the treatment of multiple sclerosis and rheumatoid arthritis, are the only two DHODH inhibitors on the market." (PMID 28807907, 2017). "Additionally, inhibition of DHODH can be beneficial for spinal cord injury and rheumatoid arthritis." (PMID 35655958, 2022). "Further studies are needed to establish whether DHODH inhibitors, aside from being of use for the treatment of chronic diseases such as rheumatoid arthritis or multiple sclerosis, may be considered as antidiabetic drugs." (PMID 34113829, 2021). "To test whether BCOR inhibition broadly sensitizes cells to DHODH blockade, we evaluated four additional inhibitors: leflunomide and teriflunomide, used clinically in multiple sclerosis (MS) and rheumatoid arthritis (RA), and the AML investigational agents AG-636 and farudodstat." (PMID 41549155, 2026). "Leflunomide, a human DHODH (HsDHODH) inhibitor currently used for the treatment of rheumatoid arthritis (RA), has been reported to have an anti-cancer and anti-viral activity." (PMID 30233375, 2018). "Leflunomide (Lef), a DHODH inhibitor, is a commercially available agent approved by US Food and Drug Administration (FDA) for rheumatoid arthritis treatment." (PMID 35169125, 2022). "In contrast to CAD inhibitors, several DHODH inhibitors including brequinar (BRQ) and teriflunomide as well as its prodrug leflunomide have reached market approval as immunosuppressive agents in rheumatoid arthritis and multiple sclerosis." (PMID 35203388, 2022).
rheumatoid arthritis (continued). "While BQ is not an approved medication, two FDA-approved low-potency DHODH inhibitors (leflunomide, teriflunomide) are effective in treating autoimmune conditions such as rheumatoid arthritis and multiple sclerosis and act to decrease the activity of auto-reactive T-lymphocytes." (PMID 38973593, 2024). "While BQ is not an approved medication, two FDA-approved low potency DHODH inhibitors (leflunomide, teriflunomide) are effective in treating autoimmune conditions such as rheumatoid arthritis and multiple sclerosis and act to decrease the activity of auto-reactive T-lymphocytes 56–58." (PMID 37066260, 2024).
leukemia (22 papers, 2019 to 2026). A malignant (clonal) hematologic disorder, involving hematopoietic stem cells and characterized by the presence of primitive or atypical myeloid or lymphoid cells in the bone marrow and the blood. "Conversely, increased DHODH expression is associated with the cancerous status of T cells in leukemia; decreased activity of its protein leads to decreased proliferation of cancer cells." (PMID 41440382, 2025). "AICAr inhibits pyrimidine synthesis at the level of UMP synthase, which acts downstream of dihydroorotate dehydrogenase (DHODH), thereby sharing a similar mechanism of leukemia differentiation as that observed with brequinar, a well-known DHODH inhibitor." (PMID 39279497, 2024). "Rapidly proliferating cells, such as leukemias and lymphomas, require more pyrimidine and are more sensitive to DHODH inhibition than normal cells, and are dependent on the de novo pathway." (PMID 36825574, 2023). "One promising avenue of research to this end is the identification of compounds such as DHODH inhibitors that can induce differentiation of leukemia cells." (PMID 35992086, 2022). "Recent studies have identified DHODH as a therapeutic target for AML, and DHODH inhibitors cause myeloid differentiation and show potent anti-leukaemia effects in several AML mouse models including the Hoxa9/Meis1 model." (PMID 36285442, 2022). "Taken together, DHODH inhibitors promote differentiation of leukemia cells, decrease levels of leukemia-initiating cells, and improve survival in vivo, which demonstrates DHODH inhibition as a strategy for AML treatment." (PMID 33971967, 2021). "DHODH inhibition also has strong effects in mixed-lineage leukemia gene MLL-fused leukemia cell lines." (PMID 33971967, 2021). "DHODH is a major contributor to mitochondrial oxygen consumption and ROS production in malignant tumor such as leukemia." (PMID 33971967, 2021). "It is shown that BAY2402234 induces differentiation and inhibits proliferation in AML cell lines across multiple AM subtypes by inhibiting DHODH, including ten leukemia cell lines representing diverse AML subtypes, with a low range of IC50." (PMID 33971967, 2021). "In the 1980s, brequinar, which still ranks as one of the most potent and selective DHODH inhibitors, was shown to work in mouse models for solid tumors as well as in a leukemia murine model." (PMID 33020720, 2020). "Studies have shown that the DHODH inhibitors are highly effective in in-vitro, in-vivo pre-clinical leukemia models and currently the clinical efficacy testing of recently developed DHODH inhibitors, BAY2402234 (NCT03404726), and ASLAN003 (NCT03451084) is underway." (PMID 33816272, 2021). "To test this hypothesis, we used 2 DHODH inhibitors, brequinar, which is currently in clinical trials for leukemia (ClinicalTrials.gov Identifier: NCT03760666) and ML390." (PMID 33201894, 2020). "AICAr shares the same mechanisms of action with well-known inhibitors of de novo pyrimidine synthesis that have been previously shown to induce uridine-dependent leukemia differentiation, such as DHODH inhibitors brequinar and leflunomide, or UMP synthase inhibitor pyrazofurin." (PMID 33176741, 2020). "Interestingly, the inhibition of DHODH in a leukemia mouse model demonstrated that uridine supplementation, through the salvage pathway, could rescue the anti-leukemic effects induced by DHODH inhibition." (PMID 31108873, 2019). "Rapidly proliferating cells, such as leukemia/lymphoma blasts, including AML, show a selective vulnerability to DHODH blockade." (PMID 35223511, 2022). "Recently, Bayer AG have reported a highly potent and selective DHODH inhibitor BAY 2402234, which exhibits strong differentiation therapy potential in preclinical leukemia models." (PMID 34123854, 2021). "We observed Menin-MLL and DOT1L inhibitors act very specifically on MLL-fused leukemia cell lines, whereas inhibitors of BET, DHODH and P-TEFb have strong effects beyond MLL-fusions." (PMID 31253180, 2019).
leukemia (continued). "Interestingly, in line with the known role of DHODH, the most dramatic effect of its knockout in this study was observed in the leukemic cell lines KBM7 and K562 (CRISPR scores − 3.4 and − 3.8, respectively), strengthening the notion for the specific role of DHODH in leukemia." (PMID 31889988, 2019).
acute myeloid leukemia (21 papers, 2017 to 2026). Acute myeloid leukemia (AML) is a group of neoplasms arising from precursor cells committed to the myeloid cell-line differentiation. "Inhibition of complex III of mitochondrial ETC by antimycin A was able to inhibit proliferation and promote cellular differentiation in acute myeloid leukemia (AML) cells through a DHODH inhibition-mediated mechanism." (PMID 37147673, 2023). "Inhibition of DHODH has been recently proposed to be effective against acute myeloid leukemia (AML), breast and colorectal cancers, and to induce ferroptosis in several cancer cell lines and patient-derived xenografts." (PMID 35912247, 2022). "Synergistic effects of DHODH and hENT1/2 inhibition were also observed in acute myeloid leukemia (AML)." (PMID 35203388, 2022). "Recent studies have highlighted DHODH inhibitors as potential anti-immunity, antiviral, anticancer, and acute myeloid leukaemia therapeutic targets." (PMID 36412986, 2022). "Our results confirm the inhibitory effect of Vidofludimus on SARS-CoV-2 replication, and we extended this observation to BAY2402234, a potent DHODH inhibitor currently developed by Bayer as a treatment of acute myeloid leukemia." (PMID 34578395, 2021). "A most recent example is a breakthrough study showing the therapeutic potential of DHODH inhibitors in the treatment of acute myeloid leukemia." (PMID 28807907, 2017). "UMP reduction by DHODH suppression may result in integral decreases in protein N-acetyl glycosylation in acute myeloid leukemia (AML), and reduction of UMP-GlcNAc promotes myeloid differentiation." (PMID 33971967, 2021). "Recent work with brequinar, a highly specific and potent DHODH inhibitor described in the 1980s, has led to the understanding that DHODH inhibitors could be effective in acute myeloid leukemia cases." (PMID 34113829, 2021). "A recent study provided a link between uridine and cell differentiation; the pharmacological inhibition of dihydroorotate dehydrogenase (DHODH), which catalyzes the fourth step in de novo pyrimidine synthesis, overcame differentiation blockade in acute myeloid leukemia cells." (PMID 31431503, 2019). "DHODH inhibitors have demonstrated anticancer activity in different preclinical tumor models, including AML, and are currently tested in a phase I trial for patients with acute myeloid leukemia and myelodysplastic syndrome (NCT04609826)." (PMID 38500877, 2024). "This study reports that AG636, an inhibitor of the metabolic enzyme DHODH, has excellent potency against acute myeloid leukemia (AML) in pre‐clinical models." (PMID 35514210, 2022). "This pioneering study defined DHODH as a metabolic regulator of differentiation in multiple subtypes of acute myeloid leukemia (AML) and DHODH inhibition emerged as a potential strategy for overcoming differentiation blockade in treating AML." (PMID 34123854, 2021). "Additionally, DHODH inhibition has shown to overcome differentiation arrest in HOXA9-expressing acute myeloid leukemia (AML) in both in vitro and mouse models of AML." (PMID 40961924, 2025). "This idea was inspired by prior observations from acute myeloid leukemia (AML) studies, in which DHODH inhibitors could terminally differentiate leukemic myeloid progenitors." (PMID 36453548, 2022). "DHODH was also shown to have a specific role in acute myeloid leukemia (AML)." (PMID 31889988, 2019). "DHODH inhibitors (DHODHi) are clinically used for autoimmune diseases and are emerging as a novel class of anticancer agents, especially in acute myeloid leukemia (AML) where pyrimidine starvation was recently shown to reverse the characteristic differentiation block in AML cells." (PMID 35514210, 2022).
acute myeloid leukemia (continued). "In general, DHODH inhibitors prevent cellular proliferation, but some of them, such as BAY 2402234, induce differentiation of acute myeloid leukemia (AML) cells." (PMID 36814599, 2023).
Miller syndrome (20 papers, 2012 to 2026). "Present genetic research appears to connect reduced orotate production to abnormalities in the dihydroorotate dehydrogenase (DHODH) gene, which causes human Miller syndrome." (PMID 39434876, 2024). "Miller syndrome is a type of acrofacial dysostosis, caused by the mutation of the DHODH gene located on 16q22." (PMID 36140726, 2022). "Biallelic variants in DHODH gene result in defects in pyrimidine biogenesis and give rise to Miller syndrome that has an autosomal recessive inheritance." (PMID 33262786, 2020). "We supplemented two known variants (p.G202A and p.G152R) into the DHODH gene causing Miller syndrome (MIM: 263750) in the normal exome and applied the rare recessive autosomal disease model filter." (PMID 28716001, 2017). "To evaluate the impact of random neutral variation on finding the causative gene, we generated a synthetic data set modeled on published cases of Miller syndrome, a rare recessive disease caused by mutations in DHODH." (PMID 23013645, 2012). "Similarly, patients with Miller Syndrome, caused by mutation of DHODH, have decreased NF-κB pathway activity." (PMID 40738904, 2025). "Given that many advances in genetics are recent, such as the discovery of the causative DHODH gene for Miller syndrome around 201080,81, misdiagnoses may be common in studies lacking genetic confirmations for FDS patients." (PMID 38801252, 2024). "A mutation in the DHODH gene located on the 16q22.2 chromosome causes Miller syndrome." (PMID 40041258, 2023). "Some examples of new disease-associated genes that have been discovered using NGS technologies are DHODH, the causative gene of the Miller syndrome, WDR35, the gene that is responsible for Sensenbrenner syndrome, and SETBP1, which is responsible for the Schinzel–Giedion syndrome (SGS)." (PMID 34827709, 2021). "Moreover, the mutations in DHODH lead to Miller syndrome, also known as postaxial acrofacial dysostosis." (PMID 29416564, 2018). "Shortly thereafter, next-generation sequencing and DNA variant analysis of four individuals with Miller syndrome, which lacked a causative disease gene at that time, resulted in the identification of that gene, DHODH." (PMID 34350142, 2021). "The DHODH dysfunction directly inhibits NF-kB activity and disrupted cell migration, diminished cellular proliferation, and increased apoptosis, which contributes to Miller syndrome." (PMID 33971967, 2021). "Finally, in a male proband from family no 7, we diagnosed Miller syndrome (MIM:263750), as we found two biallelic variants in the DHODH gene." (PMID 33262786, 2020). "In the case of Miller syndrome, for which mutations have been reported in several papers, three mutations [p.Arg135Cys (NHLBI EA, 0.0607%), p.Gly152Arg (0.120%), and p.Arg346Try (0.161%)] should be given first priority for DHODH mutation screening in Europeans but not Africans." (PMID 27219052, 2016).
multiple sclerosis (20 papers, 2014 to 2026). A progressive autoimmune disorder affecting the central nervous system resulting in demyelination. "Given that cortical hyperactivity is associated with the remission phase of multiple sclerosis in a mouse model, reduction of firing set point by cerebral DHODH inhibition may provide a new way to slow down neurodegeneration." (PMID 31047779, 2019). "The block of both pyrimidine sources retained its effectiveness even when MEDS433 was substituted with a much less potent DHODH inhibitor, teriflunomide, which is already commercialized for multiple sclerosis." (PMID 33670894, 2021). "DHODH inhibition modulates T cell mitochondrial respiration with affinity-dependent effects in multiple sclerosis." (PMID 33971967, 2021). "Substances that inhibit DHODH, such as the metabolite teriflunomide, are utilized in the form of immunomodulatory drugs in autoimmune disorders, such as rheumatoid/psoriatic arthritis and multiple sclerosis." (PMID 37240659, 2023). "The multiple sclerosis therapeutic teriflunomide is known to block the de novo synthesis of pyrimidine in mitochondria by inhibiting the enzyme dihydroorotate-dehydrogenase (DHODH)." (PMID 32426367, 2020). "The selective and reversible inhibition of dihydroorotate dehydrogenase (DHODH), a key mitochondrial enzyme in the de novo pyrimidine synthesis pathway, by teriflunomide has been shown to be a safe and effective strategy to treat patients with multiple sclerosis (MS)." (PMID 34721394, 2021).